APP (amyloid beta precursor protein)
Diseases named in the same sentence as APP in open-access papers (continued):
Sharing a sentence is not in itself a finding about the gene and the disease.
glioma (30 papers, 2008 to 2026). A benign or malignant brain and spinal cord tumor that arises from glial cells (astrocytes, oligodendrocytes, ependymal cells). "Knockdown of TNFRSF12A in glioma cells altered the expression of genes associated with amyloid precursor protein (APP) processing and Wnt signaling pathways." (PMID 40595248, 2025). "Additionally, the amyloid precursor protein (APP)—the precursor of Aβ, a hallmark of AD—has been implicated in various malignancies, and APP overexpression has been reported in glioma." (PMID 41241298, 2025). "The study revealed that pharmacologically activating PPARA with the agonists gemfibrozil and Wy14643 induces autophagy in human microglia cells and U251 human glioma cells expressing the human APP mutant (APP-p.M671L), and this induction is PPARA-dependent." (PMID 38259497, 2023). "It is worth noting that berberine can reduce the level of Aβ by altering the hyperphosphorylation of APP in human glioma H4 cells." (PMID 35795239, 2022). "The results of an IPA-based interaction network analysis confirmed that APP is an important intermediate molecule that mediates the downstream regulatory effects of OLFML2A in glioma." (PMID 34650914, 2021). "Here we report that antibodies against Aβ with relatively low reactivity against APP show Aβ immunostaining in glioma cells and nearby blood vessels in mice." (PMID 31137462, 2019). "To determine the mechanism by which both cannabinoids reduce Aβ levels first we examined the effect of both compounds on Aβ release from cultured APP/PS1 glioma cells." (PMID 22248049, 2012). "CNTN2 has been shown to promote glioma stem-like cell proliferation through regulation of EGFR-, HES1-, and APP/AICD-associated signaling pathways, and its knockdown suppresses tumor cell growth in vitro, supporting a functional role in glioblastoma progression." (PMID 41596752, 2026). "It has been shown that pharmacological activation of PPARα receptors by their agonists gemfibrozil and 2-[4-chloro-6-(2,3-dimethylanilino)pyrimidin-2-yl]sulfanylacetic acid (Wy14643) induces autophagy in HM microglial and U251 human glioma cells expressing a mutant form of human APP (APP-p.M671L)." (PMID 35457077, 2022). "In our present study, we observed that APP was expressed at low levels in glioma tissue." (PMID 34650914, 2021). "Finally, we demonstrated that APP is an important intermediate molecule that mediates the downstream regulatory effects of OLFML2A in glioma." (PMID 34650914, 2021). "In our study, we chose specific antibodies against Aβ peptides with low reactivity for the precursor APP to see whether Aβ immunoreactivity is present in glioma tumors and nearby blood vessels in mice." (PMID 31137462, 2019). "Six out of the 17 interactions have been previously linked to invasion, migration or adhesion (EPHA4-Efnb3, SEMA5A-Plxnb3, AQP4-Dag1, FGFR1-Ncam1, FGF2-Sdc2, and APP-Aplp2) whereas only 3 interactions have been previously reported in glioma (SEMA5A-Plxnb3, AQP4-Dag1, and FGF2-Sdc2)." (PMID 25365423, 2014). "The JAM, APP, MIF, and NCAM signaling pathway networks were targeted by glioma cells, endothelial cells, astrocytes, and oligodendrocytes." (PMID 38824202, 2024). "We enrolled TCGA database to analyze the correlation between APP or BACE1 and the OS of glioma patients." (PMID 37849438, 2023). "The expression of the APP gene and the BACE1 gene was positively correlated in the glioma (p < 0.001)." (PMID 37849438, 2023).
glioma (continued). "Here, we clarified that SAA inhibits the directional migration of astrocytes in vivo using APP/PS1-Saa3−/− mice and in vitro via stimulation of primary cultures of mouse astrocytes and human glioma U251 cells with recombinant human apo-SAA." (PMID 32861245, 2020). "Others were robust and shared across most samples such as CD74 receptor binding to MIF, COPA, or APP as cognate ligands and SPP1-CD44 (myeloid to glioma signaling) and TNFRSF1A-GRN, PGRMC2-CCL4L2, MDK-SORL1 or LRP1, and GPR37L1-PSAP (glioma to myeloid signaling)." (PMID 35140215, 2022). "Though the level of the APP gene was not significantly different within the LGG and HGG patients, the high level of the BACE1 gene was positively correlated to the longer survival of glioma patients (p < 0.01)." (PMID 37849438, 2023).
Onset (30 papers, 2010 to 2026). The age group in which disease manifestations appear. "Familial or early-onset AD, which represents less than 5% of all cases, is primarily associated with mutations in genes such as amyloid precursor protein (APP) and presenilin 1 and 2 (PSEN1 and PSEN2)." (PMID 41155642, 2025). "Rare forms of dominantly inherited early-onset AD can result from mutations in the amyloid precursor protein (APP) and presenilin (PSEN1 and PSEN2) genes, collectively accounting for less than 1% of all AD cases." (PMID 38002991, 2023). "APP mutations underlie familial, early-onset AD, and the involvement of APP in AD pathology has been extensively studied." (PMID 31174368, 2019). "Five percent of AD develops early in life (familial/early‐onset AD [EOAD]) facilitated by mutations in Amyloid Precursor Protein (APP), presenilin 1, Tau, or APOE genes." (PMID 29943428, 2018). "This hypothesis emerged with the discovery of dominant missense mutations in the amyloid precursor protein (APP) associated with early-onset familial Alzheimer’s disease (FAD) that alter Aβ production." (PMID 39932776, 2025). "Genetic factors also modulate disease risk: the apolipoprotein E (ApoE) ε4 allele is the strongest known genetic susceptibility factor for late-onset AD, whereas mutations in amyloid precursor protein (APP), presenilin-1 (PSEN1), and presenilin-2 (PSEN2) cause rare familial forms of early-onset AD." (PMID 41373799, 2025). "Early-onset AD is a rare hereditary form of the disease that accounts for ~5-10% of all cases and a minority of early-onset cases has been linked to specific mutations in the genes encoding amyloid precursor protein (APP), presenilin 1 (PSEN1), and presenilin 2 (PSEN2)." (PMID 34712240, 2021). "For example, early-onset AD has been linked to mutations in the genes encoding amyloid precursor protein (APP) and the presenilins (PS-1 and PS-2) involved in amyloid-β processing, while the ε4 allele of the apolipoprotein E gene has been identified as a risk factor for late-onset AD." (PMID 30110885, 2018). "There are two varieties of AD: “early onset forms” (ADAD, less than 5% of all cases) connected to mutations in the presenilin 1/2 (PS-1/2) and amyloid precursor protein (APP) genes and “late-onset AD” (LOAD), the most frequent sporadic form of the illness." (PMID 37371547, 2023). "As an initial target gene for A-to-G base editing, we chose amyloid precursor protein (APP), which is mutated in familial early-onset Alzheimer’s disease." (PMID 32393762, 2020). "The remaining 2%–5% of cases are early‐onset AD (EOAD) that are linked to genetic mutation(s) in genes involved in amyloid metabolism, such as Amyloid Precursor Protein (APP), Presenilin 1 (PSEN1), and Presenilin 2 (PSEN2)." (PMID 32857910, 2020). "The genes primarily involved in AD are Amyloid Precursor Protein (APP), Presenilin 1 (PSEN1), and Presenilin 2 (PSEN2), which are associated with early-onset familial AD (fAD), variations in apolipoprotein E (APOE) gene increase the risk of late-onset sporadic AD (sAD)." (PMID 39861466, 2025). "Familial AD is associated with mutations in amyloid precursor protein APP, and presenilins (PS1 and PS2), while late-onset AD is associated with mutations in APOE and other genes involved in vascular dysfunction, immunity and inflammation, cholesterol metabolism, endocytosis, and ubiquitination." (PMID 38255267, 2024). "Furthermore, mutations in three common genes—amyloid precursor protein (APP), presenilin-1 (PSEN1), and presenilin-2 (PSEN2) are associated with early-onset AD (EOAD), developing in fourth or fifth decade of life." (PMID 33815092, 2021). "However, three early-onset familial AD genes (APP, PSEN1, and PSEN2) and one genetic risk factor for late-onset AD (APOE) have been identified." (PMID 31080696, 2019). "Both APP p.R499C and p.R397T were found in late-onset PD (LOPD; AAO >50 years) patients whereas APP (p.Q138R) and GRN (p.C260R) were found in controls." (PMID 29692703, 2018).
Onset (continued). "It is important to note that in healthy individuals, the ∝–secretase enzyme is used to cut APP instead of BACE1, suggesting a strong correlation between elevated levels of the BACE1 and late-onset Alzheimer’s in patients." (PMID 26543800, 2015).
atherosclerosis (27 papers, 2009 to 2025). A disease characterized by the build-up of fatty material and calcium deposition in the arterial wall resulting in partial or complete occlusion of the arterial lumen. "In our study, CE(22:6) and CE(22:4)—associated with atherosclerosis—were elevated in the hippocampus of APP/PS1 mice." (PMID 40693114, 2025). "Platelet-derived APP stimulate pro-inflammatory signaling to promote atherosclerosis development while APP-deficiency reduces atherosclerotic plaque size in mice." (PMID 32987857, 2020). "We identify a key macrophage subgroup (C2 FCN1+ macrophages) associated with atherosclerosis, which interacts with endothelial cells via CCL, CXCL, APP, and other pathways to regulate disease progression." (PMID 39726810, 2024). "C2 FCN1+ macrophages interact with endothelial cells via CCL, CXCL, APP, and other pathways to regulate the progression of atherosclerosis." (PMID 39726810, 2024). "Brain hypoxia, which can result from advanced atherosclerosis, has been shown to significantly increase the cleavage of Aβ from the APP via upregulation of the β- and γ-secretase enzymatic pathways." (PMID 26136682, 2015). "Notably, among all EC subtypes, Endo1 cells showed the highest expression of APP, and APP levels positively correlated with migrasome scores in two independent atherosclerosis datasets (GSE132651 and GSE28829; r = 0.556, p = 0.048; r = 0.597, p = 0.015)." (PMID 40548932, 2025). "Furthermore, platelet-derived APP in atherosclerosis is processed by protein hydrolysis to Abeta, which promotes inducible nitric oxide synthase expression and thus induces macrophage activation." (PMID 39351084, 2024). "A series of single-cell sequencing analysis methods were used to infer the cell trajectory and identify the key macrophage subsets C2 FCN1+ macrophages associated with atherosclerosis, and interact with endothelial cells through CCL, CXCL, APP, and other pathways." (PMID 39726810, 2024). "In conclusion, we identified the key macrophage subpopulation C2 FCN1+ macrophages associated with atherosclerosis by using a series of methods of single-cell analysis and interacted with endothelial cells through CCL, CXCL, APP, and other pathways to regulate the progression of atherosclerosis." (PMID 39726810, 2024). "Therefore, the deleterious vascular effects of Aβ are likely to act synergistically with large artery atherosclerosis to aggravate cerebral perfusion, which, in turn, promotes amyloidogenesis by increasing APP cleavage." (PMID 26136682, 2015). "In humans, this protein belongs to negative APP and lowered plasma levels of apoA-I is considered to be correlated to an increased risk of cardiovascular diseases and atherosclerosis." (PMID 24885808, 2014). "In APP knock-out mice, cholesterol is strongly increased, and APP knockout has a number of additional cholesterol- and lipid-related consequences, including reduced diet-dependent atherosclerosis and increased Niemann-Pick cholesterol phenotype." (PMID 24575399, 2013). "LRPs are known to regulate APP's endocytic trafficking, and seem to be a hub of a number of mounting evidences on processes that link to cholesterol metabolism and atherosclerosis." (PMID 20405009, 2010). "Additionally, preclinical studies have shown links between APP and increased atherosclerosis." (PMID 30893771, 2019). "We characterize hemodynamic responses and cognitive performance in APP/PS1 Alzheimer’s mice, atherosclerosis mice, and a mixed disease group (APP/PS1 and atherosclerosis) between the ages of 9 and 12 months." (PMID 40405889, 2025). "We also found certain HS disaccharides (D0H0) associated with APP and other proteins increased in CAA (OLFML3, FRZB, ApoE, FGA), as well as with ApoE genotype, but not with atherosclerosis." (PMID 40156913, 2025).
atherosclerosis (continued). "The late stage of atherosclerosis might bear similarities to CAVD development, suggesting that in diseased aortic valves prone to calcify, APP can be released from activated platelets and may participate in the initiation of calcification." (PMID 32987857, 2020). "The present findings extend these concepts to the gene network level, and delineates pathways related to NF-κB and TNF that are involved in inflammation and atherosclerosis, as well as focus genes related to ubiquitin, proteasome, histone, HNF4A, insulin and APP." (PMID 23874591, 2013). "Since this diet may also induce atherosclerosis in some mouse models, we verified that APP/PS1 mice exposed to the diet did not develop atherosclerotic plaques (data not shown)." (PMID 31130652, 2019). "Transgenic APOE−/− mice overexpressing APP show atherosclerotic lesions of increased size and with enhanced inflammation in comparison with APOE−/− mice, while APOE−/− mice lacking APP have less atherosclerosis than APOE−/− mice." (PMID 30893771, 2019).
schizophrenia (27 papers, 2009 to 2024). A major psychotic disorder characterized by abnormalities in the perception or expression of reality. "One of the network clusters contained APP along with several previously implicated schizophrenia genes." (PMID 31174177, 2019). "APP has been listed in the HGMD as being associated with schizophrenia." (PMID 22373040, 2011). "Lower satisfaction with treatment, higher QOL in the mental domain, younger age of onset, more side-effects, higher doses of antipsychotics were observed among schizophrenia patients with APP treatment." (PMID 38002537, 2023). "The result was that intensity APP (molecular masses of 130 kDa) and APP ratio were significantly reduced in schizophrenia patients compared to the controls." (PMID 34679416, 2021). "Decreased CSF APP level was observed in patients with schizophrenia and those with BD, which is consistent with previous studies reporting impaired neuroplasticity in patients with schizophrenia and those with BD4,7." (PMID 32439851, 2020). "Sample ontology–disease trait pairs link APP-5′AS expression to the brain and type 2 diabetes and schizophrenia." (PMID 30610612, 2019). "A study about CSF APP levels in patients with schizophrenia or bipolar disorder by Hidense and collaborators suggested that neuroplasticity-associated proteins may be used as markers in psychiatric disorders." (PMID 34679416, 2021). "They found decreased CSF APP level in patients with schizophrenia or bipolar disorder." (PMID 34679416, 2021). "CSF amyloid precursor protein (APP) and glial cell-derived neurotrophic factor (GDNF) levels were significantly lower in patients with schizophrenia, and CSF APP and neural cell adhesion molecule (NCAM)-1 levels were significantly lower in patients with BD, than in healthy controls (all p < 0.05)." (PMID 32439851, 2020). "The polymorphism of APP has also been associated with schizophrenia as listed in HGMD, although its gene expression was not significantly different in disease samples of this study." (PMID 22373040, 2011). "The APP/PS1 and Tg2576 mice, as well as selective dopaminergic receptors, cause a blockade in the pre-limbic region of the prefrontal cortex or STOP-null mice modeling schizophrenia, also show a reduction of spontaneous alternation, suggesting its relation to frontal hypofunctionality." (PMID 34199476, 2021). "Notably, studies on schizophrenia and bipolar disorder seem to agree on the altered metabolism of APP, probably connected to an unknown neurodevelopmental process." (PMID 34679416, 2021). "In addition, mutations of other γ-secretase substrates such as APP or N-Cadherin have not been previously shown to cause schizophrenia-like behavioural deficits in mice or to be associated with schizophrenia." (PMID 24891237, 2014). "CSF APP and GDNF levels were decreased in patients with schizophrenia, while CSF APP and NCAM-1 levels were decreased in patients with BD, compared with healthy controls." (PMID 32439851, 2020). "Seven genes, APP, ERBB3, FEZ1, HSPA2, SERPINI1, SOX10 and SYN2, display altered expression in studies of schizophrenia or bipolar disorder." (PMID 19300510, 2009). "Changes in cortexin 3/DISC1/APP interactions could, therefore, result in altered expression and distribution of NMDA receptors as has been observed in schizophrenia (review:)." (PMID 25889058, 2015). "While no APP-Fe-Schizophrenia axis has been found, that APP activity includes significant regulation of Fe homeostasis suggests that the miR-346/IRP-1/Fe pathway may function in other neurological disorders." (PMID 30470799, 2019).